HNRNPM (heterogeneous nuclear ribonucleoprotein M)
Diseases named in the same sentence as HNRNPM in open-access papers (continued):
Sharing a sentence is not in itself a finding about the gene and the disease.
viral infection (6 papers, 2017 to 2025). "Firstly, viral infection caused export of hnRNPM from the nucleus to cytoplasm, indicating a cytoplasmic role of hnRNPM after viral infection." (PMID 31433824, 2019). "Viral infection caused translocation of hnRNPM from the nucleus to the cytoplasm." (PMID 31433824, 2019). "HnRNPM is a pre-mRNA binding protein and part of the spliceosome complex, and has been proposed to be a host target in regulating viral infection." (PMID 40853910, 2025). "Viral infection led to export of hnRNPM from the nucleus to the cytoplasm, at where it impaired the binding of RLRs to viral RNA and subsequent innate antiviral response." (PMID 31433824, 2019). "We further examined the cellular localizations of hnRNPM before and after viral infection." (PMID 31433824, 2019). "In addition, the hnRNPM translocation after viral infection was inhibited in RIG-I knockdown cells." (PMID 31433824, 2019). "Although it seems hnRNPM formed puncta structures in cytoplasm after virus infection, confocal microscopy experiments showed that hnRNPM was not co-localized with G3BP1 (as a marker of stress granules)." (PMID 31433824, 2019). "Our results show that knocking down hu-hnRNPM reduces the levels of M1 and M2 proteins but does not affect the expression of PB2 and NP proteins, consistent with observations from viral infection." (PMID 40434105, 2025).
colorectal cancer (5 papers, 2017 to 2024). A primary or metastatic malignant neoplasm that affects the colon or rectum. "The development of colorectal cancer is associated with elevation of hnRNPM and is associated with poor prognosis." (PMID 33381452, 2020). "In this paper, we found, that in colorectal cancer cells, the long non-coding RNA H19 can bind immature RNAs and splicing factors as hnRNPM and RBFOX2." (PMID 39098911, 2024). "Previous studies have reported that HNRNPM upregulation is correlated with poor outcomes and chemoresistance in sarcoma patients, as well as with poor outcomes in colorectal cancer patients." (PMID 33466816, 2021). "Although the mechanism of influence of hypoxic condition remains unelucidated in colorectal cancer; Chen & colleagues demonstrated the influence of hypoxia on hnRNPM." (PMID 33381452, 2020). "Also, the upregulation of HnRNPM (ranked 13th in patient TCGA-BH-A0H9) is contained in the human colorectal epithelial tumorigenesis and could serve as a tumor biomarker for colorectal cancer." (PMID 38254011, 2024).
prostate carcinoma (5 papers, 2019 to 2024). A carcinoma that arises from epithelial cells of the prostate gland. "In contrast, a decrease in HNRNPM expression was shown to be correlated with a more aggressive phenotype in prostate cancer." (PMID 33466816, 2021). "In contrast, HNRNPM expression has been reported to be significantly lower in prostate cancer than that in normal prostate tissues." (PMID 33466816, 2021). "Further, YY1 also contributes to the metastatic potential of the prostate cancer cells by mediating transcriptional repression of heterogeneous nuclear ribonucleoprotein M (hnRNPM), which is an inhibitor of migration and invasion of prostate cancer cells." (PMID 31824839, 2019). "A pooled shRNA screen identifies HNRNPM as a regulator of prostate cancer (PCa) cell growth." (PMID 34075878, 2021). "Furthermore, HNRNPM downregulation was found to be correlated with more aggressive characteristics of prostate cancer cell lines, while low HNRNPM expression levels were shown to promote invasion and migration in prostate cancer." (PMID 33466816, 2021).
cognitive decline (3 papers, 2019 to 2024). "Depletion of HNRNPM (0.472-fold), which encodes an RNA-binding protein, resulted in cognitive decline, the loss of synaptic proteins, and alterations in dendritic spine density." (PMID 39335533, 2024). "We present here evidence to suggest that expression levels of HNRNPM, HNRNPA0 and AKAP17A genes may be associated with cognitive decline, whilst AKAP17A levels may be associated with decline in physical performance in a human population." (PMID 31292793, 2019).
colon cancer (3 papers, 2011 to 2024). "An increase in HNRNPM expression was found to be correlated with the pathogenesis of ovarian cancer and poor outcome of colon cancer and Ewing sarcoma, as well as invasion and metastasis in breast and colon cancer." (PMID 33466816, 2021). "Moreover, HNRNPM was also found to promote tumor growth, invasion, and metastasis in breast and colon cancer." (PMID 33466816, 2021).
lung adenocarcinoma (3 papers, 2021 to 2025). A carcinoma that arises from the lung and is characterized by the presence of malignant glandular epithelial cells. "Assays conducted in Calu-3, Panc-1, SKMEL147, and MEL501 cell lines, representing lung adenocarcinoma, pancreatic adenocarcinoma, and melanoma, respectively, showed that HNRNPM loss resulted in growth inhibition, similar to what we had observed with PCa." (PMID 34075878, 2021). "Heterogeneous nuclear ribonucleoprotein M (hnRNPM) serves as a novel interaction partner for PARP4 and regulates the tumorigenesis of lung adenocarcinoma (LUAD)." (PMID 40904702, 2025). "PARP4 is a novel modulator of lung adenocarcinoma, where its tumor suppressive activity is mediated not through the vault complex—unlike conventionally thought, but in association with its novel interaction partner hnRNPM, thus suggesting a role for splicing dysregulation in LUAD tumorigenesis." (PMID 39034402, 2024).
diabetes (2 papers, 2021). "Additionally, HNRNPM mRNA levels, which are high in normal pancreatic tissues, were found to be markedly reduced in cancer patients when compared with healthy subjects and patients with diabetes." (PMID 33466816, 2021). "Elevated levels of glucose, such as exhibited in individuals with diabetes, led to both the upregulation of CUG-BP and the downregulation of hnRNPM." (PMID 34573314, 2021).
esophageal cancer (2 papers, 2016 to 2020). A primary or metastatic malignant neoplasm involving the esophagus. "Survival analysis demonstrates that the high expression of HNRNPM and SRSF1 in esophageal cancer might be a poor prognostic marker." (PMID 32903837, 2020).
frontotemporal dementia (2 papers, 2021 to 2024). Frontotemporal dementia (FTD) comprises a group of neurodegenerative disorders, characterized by progressive changes in behavior, executive dysfunction and language impairment, as a result of degeneration of the medial prefrontal and frontoinsular cortices. "Furthermore, HNRNPM interacts with other binding proteins in biological processes that are important for neuronal health, while the larger family of HNRNPs have been implicated in frontotemporal lobar degeneration and amyotrophic lateral sclerosis." (PMID 39335533, 2024).
liver cancer (2 papers, 2022 to 2024). An epithelial or non-epithelial malignant neoplasm that arises from the liver. "The heterogeneous nuclear ribonucleoprotein M (HNRNPM) is involved in tumor immune escape and is elevated in liver cancer." (PMID 36569303, 2022). "Furthermore, the KIS interactome in liver cancer cells revealed a significant enrichment of potential KIS interactors in mRNA splicing, including hnRNPM and PTBP1." (PMID 38597390, 2024).
melanoma (2 papers, 2021 to 2024). A malignant, usually aggressive tumor composed of atypical, neoplastic melanocytes. "The results displayed that hnRNPM was significantly upregulated in the cancerous tissues of melanoma patients compared to that of the normal tissues." (PMID 39068483, 2024). "In addition, we have shown that cells derived from other cancer types (PANC-1, Calu3, melanoma) are sensitive to HNRNPM knockdown." (PMID 34075878, 2021). "We confirmed that the expression of the HNRNPM-dependent circRNAs, which we identified in PCa, is significantly negatively correlated with HNRNPM expression (R = −0.42, p<2.2e-16) across 10 different primary melanoma cell lines." (PMID 34075878, 2021).
pancreatic cancer (2 papers, 2020 to 2021). "However, whether HNRNPM plays a role in pancreatic cancer remains unknown." (PMID 33466816, 2021).
poliovirus infection (2 papers, 2018 to 2021). An disease or disorder caused by infection with Enterovirus C. "To validate the peptide-level analysis and the data more broadly, we selected heterogeneous nuclear ribonucleoprotein M (hnRNP M) as a positive control due to recent work demonstrating the relocalization of this protein to the cytoplasm during poliovirus infection." (PMID 30142213, 2018).
Salmonella Infections (2 papers, 2021 to 2025). Infections with bacteria of the genus SALMONELLA. "Up regulation of hnRNPM after 4 hours of Salmonella infection stimulated the chemokine receptor CCRL2, the regulator of NF-κB (NFKBIZ) pathway." (PMID 41026719, 2025).
sarcoma (2 papers, 2021 to 2025). A usually aggressive malignant neoplasm of the soft tissue or bone. "The correlation between ERCC6 and HNRNPM was analyzed using four public databases (including osteosarcoma in TARGET, sarcoma in TCGA, GSE21257, and GSE218035), and the results showed a positive correlation." (PMID 40476445, 2025).
triple-negative breast carcinoma (2 papers, 2020 to 2024). An invasive breast carcinoma which is negative for expression of estrogen receptor (ER), progesterone receptor (PR), and human epidermal growth factor receptor 2 (HER2). "However, only one study found that MORC2 mutant M276I regulated hnRNPM-mediated CD44 splicing switch to promote invasion and metastasis in triple-negative breast cancer cells." (PMID 39048555, 2024).
acne (1 paper, 2025). An inflammatory process of the sebaceous glands which is characterized by comedones, nodules, papules and/or pustules on the skin. "Central to our findings are the hub genes HNRNPA2B1, HNRNPM, and RBM39, identified through the protein–protein interaction (PPI) network analysis as key regulators of acne pathogenesis." (PMID 41614864, 2025).
atherosclerosis (1 paper, 2023). A disease characterized by the build-up of fatty material and calcium deposition in the arterial wall resulting in partial or complete occlusion of the arterial lumen. "Since SMCs were shown to differentiate towards a macrophage-like phenotype in a mouse model of atherosclerosis and they are known as being active in proinflammatory cytokine production and secretion, we may hypothesize a hnRNPM activity in SMCs similar to that described in macrophages." (PMID 37570694, 2023). "The furoxan-induced depletion of hnRNPM concentrations in VSMCs may genuinely reduce NEAT1 stability and SMC proliferation, with a conceivable in vivo decrease in SMCs’ contribution to atherosclerosis." (PMID 37570694, 2023).
cognitive deficits (1 paper, 2023). "RBM5, PNISR (also known as SFRS18) and HNRNPM code for RNA-binding proteins, and dysregulations of these genes are associated with carcinogenesis, psoriasis and cognitive deficits, respectively." (PMID 37026480, 2023).
myotonic dystrophy type 1 (1 paper, 2020). Steinert disease, also known as myotonic dystrophy type 1, is a muscle disease characterized by myotonia and by multiorgan damage that combines various degrees of muscle weakness, arrhythmia and/or cardiac conduction disorders, cataract, endocrine damage, sleep disorders and baldness. "As expected, we were able to pull down proteins known to bind RNA such as CELF2, HNRNPM, and HDLBP, as well as RBPs involved in muscle diseases such as MBNL1, which plays a key role in the pathogenic mechanism of myotonic dystrophy type 1." (PMID 33338663, 2020).
osteosarcoma (1 paper, 2025). A usually aggressive malignant bone-forming mesenchymal neoplasm, predominantly affecting adolescents and young adults. "This study utilizes patient‐derived osteosarcoma organoids and CRISPR screening to identify ERCC6 and HNRNPM as key mediators of cisplatin resistance via the PI3K/AKT pathway and BAX alternative splicing." (PMID 40476445, 2025).
pancreatic ductal adenocarcinoma (1 paper, 2021). An infiltrating adenocarcinoma that arises from the epithelial cells of the pancreas. "In this study, we found that HNRNPM is highly expressed in pancreatic tissues and that its expression is reduced in pancreatic ductal adenocarcinoma (PDA) tissues." (PMID 33466816, 2021). "Thus, in this study, we investigated the expression and effects of HNRNPM in pancreatic ductal adenocarcinoma (PDA)." (PMID 33466816, 2021).
Schistosoma haematobium infection (1 paper, 2025). "Machine learning emphasized SYNPO2, CD276, α2M, LCAT, and hnRNPM as the most discriminating biomarkers for Schistosoma haematobium infection." (PMID 40853910, 2025).
spinal muscular atrophy (1 paper, 2021). A motor neuron disease that affect the muscles, and characterized by muscle weakness and atrophy resulting from progressive degeneration and irreversible loss of the anterior horn cells in the spinal cord (i.e., lower motor neurons) and the brain stem nuclei. "It has been reported that hnRNPM is involved in carcinogenesis, spinal muscular atrophy and cell differentiation by associating with pre‐mRNAs in the nucleus and influencing pre‐mRNA processing." (PMID 33837664, 2021).
uterine corpus endometrial carcinoma (1 paper, 2020). A endometrial carcinoma (disease) that involves the body of uterus. "HNRNPM, HNRNPUL1, and HNRNPL showed high mutation frequencies, and most hnRNP genes were frequently mutated in uterine corpus endometrial carcinoma (UCEC)." (PMID 32915499, 2020).
varicocele (1 paper, 2024). A condition characterized by the dilated tortuous veins of the spermatic cord with a marked left-sided predominance. "Furthermore, in humans with an associated varicocele, the closely related exon skipping protein hnrnpM is only found in fertile, but not infertile spermatozoa." (PMID 39092172, 2024).
cancer (38 papers, 2011 to 2025). A tumor composed of atypical neoplastic, often pleomorphic cells that invade other tissues. "This corresponded to 5% of all alternatively spliced genes upon hnRNPM loss (1.71-fold over enrichment, p value = 0.011, hypergeometric test), indicating that hnRNPM was likely involved in the splicing of known cancer-associated genes." (PMID 39034402, 2024). "Recently, it has been reported that heterogeneous ribonuclear protein M (HNRNPM) is a splicing factor associated with malignant tumors." (PMID 33466816, 2021). "Pan‐cancer genetic alternations of hnRNP genes indicated that the overall average mutation frequency ranged from 0% to 14.9%, and hnRNP genes including HNRNPM, HNRNPUL1, HNRNPL showed high mutation frequencies." (PMID 32915499, 2020). "A cancer-associated Microrchidia family CW-type zinc finger 2 (MORC2) (M276I) mutant was reported to promote metastatic ability of TNBC cancer cells by enhancing interaction with hnRNPM and splicing switch of CD44 from the epithelial isoform (CD44v) to the mesenchymal isoform (CD44s)." (PMID 31737791, 2019). "CYMP-AS1 exerted pro-cancer effects by binding to hnRNPM, reducing the mRNA stability of AXIN2, and modulating the Wnt/β-catenin signaling pathway, ultimately accelerating the OC progression." (PMID 40746892, 2025). "HnRNPM influences cancer development through a variety of mechanisms, and potentially serves as a cancer marker and anti-cancer target." (PMID 40853910, 2025). "Studies have shown that hnRNPM played a unique role as CEAR in various cells, such as Kupffer cells, other terminally differentiated cells, and certain cancer cells, with its binding to CEA triggering inflammation response." (PMID 40853910, 2025). "Although CD276 and hnRNPM have roles in immune modulation and cancer, their observed patterns in individuals infected with Schistosoma haematobium in our study indicate a potentially specific involvement in this infection." (PMID 40853910, 2025). "Heterogeneous nuclear ribonucleoprotein M (hnRNPM) has been predominantly described in the context of pre-messenger RNA (pre-mRNA) splicing, cancer biology, or muscle differentiation." (PMID 39707025, 2025). "For example, circUR1 directly interacts with heterogeneous nuclear ribonucleoprotein M (hnRNPM) and modulates alternative splicing of genes involved in cell migration, which negatively impacts cancer metastasis." (PMID 39337606, 2024). "In recent years, the increasing evidence confirms that the hnRNPM protein plays a crucial role in regulating cancer stem cells properties." (PMID 39068483, 2024). "Having demonstrated hnRNPM as a prospective new association partner of PARP4, we sought to examine the underlying mechanisms by which it exerts its effects in cancer." (PMID 39034402, 2024). "In the context of cancer, hnRNPM has been reported to drive a number of tumor-supporting splicing programs or events." (PMID 39034402, 2024). "Overexpression of RUVBL1, RUVBL2, ILF2, ILF3, and HNRNPM are observed in various cancers with their progression (RUVBL1 and RUVBL222,46, ILF2 and ILF347–49, HNRNPM50,51)." (PMID 38225262, 2024). "Heterogeneous nuclear ribonucleoproteins C and M (hnRNPC, hnRNPM) are RNA-binding proteins belonging to the hnRNP family and have important roles in cancer related to their functions in processing and splicing of RNAs." (PMID 39221819, 2024). "In particular, hnRNPM has been reported to induce cytokine production, e.g., in Kupffer cells, and to regulate anoikis in cancer." (PMID 37570694, 2023). "Consistent with these cancer-promoting actions, our results showed that hnRNPM along with PLANE represses the AS event generating NCOR2-202 and thus promotes cancer cell proliferation." (PMID 34145290, 2021). "As hnRNPM stimulates mesenchymal-associated splicing and promotes cancer metastasis, we reasoned that these hnRNPM-interacting splicing factors likely affect EMT and tumor metastasis by synergizing with or antagonizing hnRNPM’s activity." (PMID 31980632, 2020).